FOXP3 (forkhead box P3)
Diseases named in the same sentence as FOXP3 in open-access papers (continued):
Sharing a sentence is not in itself a finding about the gene and the disease.
tumor (continued). "Taken together, these studies allude to the possibility that Nrp-1 expression may be a good indicator for distinguishing between peripherally induced adaptive Treg cells and may be particularly suitable in deciphering the composition of tumor-infiltrating Foxp3+ Treg cells." (PMID 23874336, 2013). "Similarly, these same CD4+Foxp3+CD25low Tregs derived from vaccinated Foxp3GFP neu-N mice suppressed high avidity T cell IFNγ secretion in vivo after they were transferred into tumor bearing FVB/N mice treated with the 3T3neuGM vaccine and high avidity T cells." (PMID 22359647, 2012). "It is likely that a similar switch could occur for tumor-infiltrating FoxP3+ T cells." (PMID 22292042, 2012). "In line with our hypothesis, FTS reduced the expression of Foxp3 in tumor cells." (PMID 22323550, 2012). "Quantification of the number of CD4+, CD8+ and FOXP3+ T-lymphocytes in progressive disease indeed confirmed a lower number of positive cells located on the endometrial-myometrial border (EM), at the edge of the tumor (Tumor Edge) and within the tumor (Intratumoral)." (PMID 22295114, 2012). "Notably, an overall trend (p = 0.02) suggesting an association between total number of FOXP3+ TIL and higher tumor stage could be observed (Stage IA: 7.1 ± 13.6, Stage IIA: 7.9 ± 13.3, Stage IIB: 7.9 ± 13.7 and Stage: IIIA: 9.5 ± 15.8)." (PMID 22471961, 2012). "Importantly, the most dramatic effect was seen in the tumor microenvironment as the absolute number of OT-II CD4+FoxP3.gfp+ T cells, assessed by flow cytometry or confocal microscopy, were reduced in mice treated with SA-4-1BBL as compared with SA treated controls." (PMID 22870329, 2012). "Given the observation of PSK and docetaxel-induced TIL enhancement, we further analyzed whether any changes in IFN-γ, IL-2, TNF-α, TGF-β, perforin, granzyme B and FoxP3 mRNA expression in the tumor micro-environment could be observed in response to the treatments." (PMID 22159900, 2012). "FoxP3 is the most definitive maker of Treg-cells, and its detection could allow a better understanding of the mechanisms through which Treg-cells are involved in autoimmune and infectious diseases, as well as transplantation and tumor immunity." (PMID 21559338, 2011). "To address the question of whether naturally occurring FoxP3+ Treg-cells are able to migrate to tumor tissues after adoptive transfer, we injected 0.5–1×106 Treg-cells that were isolated from FoxP3GFP transgenic mouse in to mice bearing CRC induced by MNU and H. pylori or healthy controls." (PMID 21559338, 2011). "Additionally, we have detected some CD4− cells expressing FoxP3 in the tumor mass." (PMID 21559338, 2011). "Several recent studies have adopted the approach to use CD127, CD25, and FOXP3 for the quantification of Treg cells in tumor-bearing individuals and could demonstrate increased numbers of CD4+CD25highCD127low Treg cells in patients with solid tumors and hematologic malignancies." (PMID 21904560, 2011). "Furthermore, repeated administration of EJHE or EJHE-WR may resulted in an increase in tumor-infiltrating CD4+CD25+Foxp3+ Treg cells that led to increase in TGF-β in tumor microenvironment." (PMID 21294856, 2011). "Thus, FOXP3+CD25- CTCL tumor cells with functional features of Tregs define a subgroup of Sézary patients who might carry a different prognosis and might require different treatments." (PMID 22151904, 2011). "Another study showed that high FoxP3 mRNA expression in tumor samples from patients with invasive ovarian cancer had poorer overall survival (27.8 vs. 77.3 months, p = 0.0034) and progression-free survival (18 vs. 57.5 months; p = 0.0041) when compared with patients with lower FoxP3 mRNA expression." (PMID 20146807, 2010).
tumor (continued). "The fact that most CD4+ T cells were also positive for Foxp3 shows that at different points of time during carcinogenesis in this model, an increasing number of phenotypical regulatory T cells (Tregs) were detectable at the tumor site demonstrating a potential protumoral effect." (PMID 20205946, 2010). "Additionally, the combination of tumor infiltrating Foxp3+ cells and GrB+ activated CTL was associated with the survival of late stage patients: a higher number of Foxp3+ and GrB+ cells was associated with a longer OS and PFS compared to a lower number of Foxp3+ and GrB+ cells (P < 0.001)." (PMID 20064222, 2010). "In addition, the analysis of mRNA levels does not allow for the attribution of FOXP3 expression to specific cell types present in the tumour and may be influenced, for example, by tumour cells expressing FOXP3 mRNA." (PMID 18985040, 2008). "Interestingly, most of FOXP3 intensely stained Tregs were found in close proximity to tumor cells." (PMID 18294387, 2008). "Regulatory T cells (Tregs) within the tumor microenvironment (TME) exhibit functional heterogeneity, including a Foxp3+T-bet+ subset known as Th1-type Treg (Th1-Treg) cells that exert potent immunosuppressive activity." (PMID 42206029, 2026). "There was insufficient tumor remaining from d1 of Patient#1; so values for CD8, CD4, and FoxP3 infiltrates from the single‐color IHC were used as baseline values for this patient." (PMID 41514118, 2026). "In terms of the tumor immune microenvironment, PD-L1-negative tumors exhibited sparse infiltration of CD8+ T cells and FOXP3+ Tregs, whereas tumors with the MT pattern showed abundant stromal infiltration of both cell types." (PMID 42038463, 2026). "At the tumor cell level, PD-L1, VISTA, COPB2, and FOXP3 expression on malignant keratinocytes themselves contribute to bidirectional immunosuppression." (PMID 41562715, 2026). "Results revealed that tissue culture supplementation with IL-2 significantly reduced T regs within the TME via inhibiting the tumor expression of CD25 and Forkhead box P3 (FOXP3)." (PMID 42192107, 2026). "Multiple immune cell markers were evaluated, including T cell markers, CD3, CD4, CD8; the macrophage marker CD68; CK-SOX10 tumor marker; and immune modulatory factors, PD1, PDL1, FOXP3, IFN-γ, NOS2, and COX2." (PMID 40663402, 2025). "In the tumor parenchyma, the proportion of YAP1-positive cells was positively correlated with the proportion of CD4-positive cells and FOXP3-positive cells (r = 0.732, P = 0.004; r = 0.5780, P = 0.03)." (PMID 40051494, 2025). "An accumulation of FoxP3+ immune cells (Tregs), potentially acting through the CTLA-4 immune checkpoint, appears to contribute to immunosuppression, tumor progression, and metastasis." (PMID 41230456, 2025). "We employed immunostaining for CD3, CD4, CD8, Granzyme B (GzmB), FOXP3, CD163, and CD68 markers to quantitively analyze the STR patient’s tumor immune landscape both at baseline and during STR 10–12." (PMID 40594889, 2025). "While specific CD4+ subtypes (Foxp3+ Tregs vs Foxp3- helper cells) were uncharacterized, enhanced MT218-MRMI signals likely reflect combined tumor and T cell EDB-FN secretion, providing a dynamic TME marker of therapeutic response." (PMID 41041061, 2025). "Cu2-induced ICD was ferroptosis-dependent and enabled significant tumour growth prevention and effective antitumour immune response (increased CD8+ T-cell infiltration and decreased Foxp3+ T-cells) in vaccinated c57BL/6 mice challenged with colorectal cancer." (PMID 40160356, 2025). "X-chromosomes are equipped with more immune functional genes including TLR7, FOXP3, and CD40L, and epigenetic modifying genes such as KDM6A, while X chromosome inactivation (XCI) upregulates or impairs anti-tumor immunity of various immune cells." (PMID 40303343, 2025).
tumor (continued). "Using bulk RNA sequencing and immunofluorescence (IF) for EMT (E‐cadherin and vimentin) and lymphocyte markers (CD3, CD8, FOXP3), we analyzed pre‐ and post‐NAC tumor samples from 100 early‐BC patients treated with NAC." (PMID 39912409, 2025). "To explore the potential repurposing of FDA-approved drugs for tumor immunotherapy, we screened FDA-approved drugs for their ability to disrupt the complex of FOXP3/RUNX1." (PMID 39979425, 2025). "In this model, the anti-tumor effects of MSU-42011 are due to its ability to reduce tumor-promoting CD206+ macrophages and FOXP3+ Tregs and increase tumor-killing cells." (PMID 40563570, 2025). "In vivo, shikonin reduced the percentage of regulatory cells (CD25+ Foxp3+ T cells) in spleen, increased the percentage of CD8+ T cells, and inhibited tumor growth." (PMID 40689201, 2025). "t-SNE visualization indicated a significantly higher distribution density of FOXP3, IL10, TGF-β1, and CTLA4 positive cells in the tumor group compared to the normal group, with gene expression concentrated in immune subpopulations like T cells." (PMID 41438510, 2025). "FX1 administration reduced the expression of Foxp3, CD25, GITR, and ICOS in Treg cells from the dLNs, but had little impact on the expression of these molecules in tumor-infiltrating Treg cells." (PMID 40290124, 2025). "Foxp3+ Tregs are typically enriched in tumors such as AML and contribute to the formation of an immunosuppressive environment that inhibits anti-tumor immune responses." (PMID 40236710, 2025). "In vivo experiments demonstrated that BN1 effectively reduced tumor burden while exhibiting immunostimulatory effects, including the increase of CD8+ IFNγ+ cells, the decrease of CD4+ Foxp3+ cells, and the regulation of cytokines." (PMID 40885393, 2025). "Histological examinations showed enhanced DC maturation and inhibition of tumour immunosuppression, as indicated by a favorable CD8+/Foxp3+ ratio." (PMID 40160356, 2025). "Expression of immune-related proteins: The expression levels of immune suppressive-related proteins FOXP3 and TGF-β1 in tumor tissues were detected by Western blot (9E a-b)." (PMID 41438510, 2025). "The results indicated a positive relationship between the expression of CCR8 and Foxp3 and a higher level of CCR8 in primary tumor tissues relative to that in the adjacent normal tissue." (PMID 40186298, 2025). "Stroma cell labeling indices of CD4**, CD8*, Foxp3*, CD68*, CD163**, and CD11c* were significantly higher in both the tumor core and the invasive front of cSCC samples as compared to BCC (*p < 0.001; **p < 0.050)." (PMID 41068337, 2025). "Autoclaved Schistosoma mansoni antigen also enhanced immune responses by increasing CD8+ T cells infiltration and decreasing FoxP3+ expression, resulting in a higher CD8+ T cells/FoxP3+ ratio within the tumour microenvironment." (PMID 40247360, 2025). "Specifically, FOXP3 expression peaks in stage III OSCC and then sharply decreases in stage IV, suggesting an inflection point in the tumor immune microenvironment." (PMID 40806346, 2025). "Composite indices were generated to quantify immune suppression (PD-L1, PD-1, LAG3, FOXP3, IDO, CD68), CAF activation (SMA, Vimentin), endothelial activation (CD31), and tumor proliferation (Ki67)." (PMID 41595458, 2025). "Meanwhile, the density of YAP1-positive cells in the tumor parenchyma was positively correlated with the density of CD4-positive cells and FOXP3-positive cells (r = 0.635, P = 0.02; r = 0.573, P = 0.04)." (PMID 40051494, 2025). "Recent studies have highlighted that A2AR expression is significantly correlated with HIF-1α, CD73, CD8, and Foxp3, and that blocking A2AR significantly reduces the number of CD4+Foxp3+ Tregs while enhancing CD8+ T cell anti-tumor responses." (PMID 40444100, 2025).
tumor (continued). "Our findings reveal that lidocaine modulated the anti-tumor effects by decreasing IL-10, TGF-β, and IL-35 levels in CD4+CD25+Foxp3+TIICs, decreasing PD-1, and increasing IFN-γ expression in cytotoxic CD8+TIICs through the NF-kb pathway." (PMID 40244064, 2025). "To confirm this, we looked at tumor infiltrating T cell profile using flow cytometry and observed CD4+ FOXP3+ Treg cells increased significantly (~9.5 folds) in D14 biopsy samples compared to pretreatment sample, i.e. D0." (PMID 40386779, 2025). "To examine this, primary CD4+ T cells were transduced with TCR1, a high-affinity TCR which we have previously shown can mediate tumor rejection in the context of ACT, or with either TCR16 or TCR18, each of which were isolated from a single FoxP3+ cell." (PMID 40196575, 2025). "Panel 3 complements Panels 1 and 2, as it was designed to assess LAG-3 expression on cytotoxic T cells (CD8+LAG-3+), macrophages (CD68+LAG-3+), NK cells (CD56+LAG-3+), Treg cells (FOXP3+LAG-3+) and tumour cells (SYN+LAG-3+)." (PMID 41285059, 2025). "Tumor samples were evaluated using immunohistochemistry (IHC) to assess CD4+ and FOXP3+ TILs in intratumoral and stromal regions." (PMID 41007768, 2025). "The observed trend indicates that CAFs expressing FAP as well as CD68 + macrophages and tumor-infiltrating lymphocytes (TILs) (CD4, CD8, and CD4 + FOXP3 +) are more abundant in the more aggressive ccRCCs." (PMID 39751643, 2025). "Tumor-secreted soluble factors, such as transforming growth factor-beta (TGF-β) and PD-L1, can induce FOXP3 expression in conventional CD4+ T cells, resulting in the generation of Tregs with immunosuppressive capabilities." (PMID 40867165, 2025). "In the tumor bed, we found a significant decrease in the percentage of CD4+Foxp3+GFP+ Tregs in mice depleted of CD8+ T cells." (PMID 40553564, 2025). "This tumor development was prevented when CD4+, CD25+, FOXP3+ Tregs were depleted, indicating that T. muris infection influences CRC through immunosuppression mediated by Tregs." (PMID 41011849, 2025). "To spatially characterize TIL-B infiltration and interaction with other immune subsets, we compared five TIL-B-poor and six TIL-B-rich OCSCC using an m-fIHC panel optimized for tumor cells, CD163+ macrophages, CD4+, CD8+, and FoxP3+ regulatory T-lymphocytes." (PMID 39796740, 2025). "In contrast, administering CCL20 via intratumoral injection in subcutaneous HCC mouse models restored tumor growth, reduced the CD8+ T cell infiltration, increased the frequency of CD4+CD25+Foxp3+ Tregs and CCR6+ Tregs in shGal1 tumors." (PMID 39853961, 2025). "At lower %sO2, where oxygen unloading into the tumor TME was greater, we observed greater frequencies of CD8 and CD4 + FoxP3- effector T cells (Teffs) in CT26 tumors." (PMID 40594309, 2025). "M1 macrophage-derived EVs similarly induce tumor death by decreasing the expression levels of CCR4, Foxp3, and CTLA-4 in canine peripheral mononuclear cells cocultured with tumor cells." (PMID 40530018, 2025). "Another study similarly validated that tumour‐infiltrating CD8+ T cells can be identified through the biomarker groups CD8, CD3, forkhead box P3 (FOXP3) and CD20 expression." (PMID 39764760, 2025). "In particular, the vaccination assay conducted in vivo demonstrated that tumour volume was 4.59-fold smaller than the control and that the ratio of immunostimulant cytotoxic T-cells (CD8+) against immunosuppressive Foxp3+ T-cells was 4.9-fold higher." (PMID 40160356, 2025). "Alternatively, sorted T cells from mice harboring conditional TXNRD1 knockouts showed reduced FOXP3 and GITR expression in the naïve state and reduced tumor burden when challenged with B16F10." (PMID 41300507, 2025). "Flow cytometric analysis of tumor-infiltrating lymphocytes confirmed these immunological features, demonstrating CD8+ T cell inactivation and Foxp-3+ Treg cell induction." (PMID 40139191, 2025).
tumor (continued). "Analysis of clinical tumor samples indicated that high expression of VSIG4 correlated with low CD8+ T cell infiltration and high Foxp3+/CD8+ T cell ratio." (PMID 39920772, 2025). "The numbers of CD4+ and forkhead box protein P3 (Foxp3)+ T cells infiltrating and accumulating in the RENCA tumor were assessed by immunohistochemical staining with anti‐CD4 and Foxp3 antibodies." (PMID 40371846, 2025). "Multiple studies have shown that cancer‐tissue‐infiltrating T cells are predominantly high‐effector Treg (FOXP3+ and CTLA4+) in a majority of cancers and hinder effective tumor immunity in humans." (PMID 40860436, 2025). "The HMP1G NPs group exhibited a significant CD8+ T cell infiltration in the tumor bed, along with an increase in GrzB levels, and a decrease in the number of CD4+ T cells and the level of Foxp3." (PMID 39661740, 2025). "LKB1, PD-L1 on tumor cells and on tumor immune-infiltrating cells, CD8, and FOXP3 were evaluated by immunohistochemistry (IHC), categorized according to predefined cutoffs." (PMID 40255421, 2025). "Treg cells, especially FoxP3+ cells, were considered as adverse predictors for several cancers, and the efficacy of PD1 blockade in intrahepatic tumours was recovered by targeting lactic acid metabolism of Treg cells." (PMID 40356247, 2025). "Elevated TNF-α levels in the CRC tumor microenvironment promote the upregulation of CCR8 on Tregs via the TNFR2/NF-κB signaling pathway and FOXP3 transcription factor activity." (PMID 40308582, 2025). "An overview of the immune cell profiles across seven tumor samples further confirmed consistent F4/80 and CD4 signals, with PD-1 and FoxP3 detected only in a subset of tumors." (PMID 41208884, 2025). "FOXP3, a canonical marker of regulatory T cells (Tregs), was significantly upregulated in CD4+ T cells from tumor tissues compared to adjacent controls (1.100 vs. 0.469, P < 0.05), indicating an accumulation of immunosuppressive Tregs within the TME." (PMID 41181122, 2025). "For example, anti-CD47 antibody-regulated phagocytosis of tumor cells by macrophages primes the proliferation of CD8+ T cells both in vitro and in vivo and lead to reduction of FoxP3+ regulatory T cells (Tregs) in vitro." (PMID 40070841, 2025). "We identified specific subtypes of stromal and immune cells critical to forming a pro-tumor microenvironment in metastatic lesions, including CCL2+ macrophages, exhausted cytotoxic T cells, and FOXP3+ regulatory T cells." (PMID 40858590, 2025). "Studies show increased Treg infiltration in CRC tissues compared to normal tissues, correlating with higher TNM stages and elevated mRNA expression of Foxp3, IL-10, and TGF-β1 in tumor-infiltrating CD4+ T cells." (PMID 40308582, 2025). "Tumor-infiltrating CD4 and CD25 human Treg (iTreg or activated CD4+CD25+ T cells) can express high levels of FoxP3 but express low levels of CD127, because downregulation of the CD127 is associated with the acquisition of regulatory function by T cells." (PMID 40244064, 2025). "In the tumor microenvironment (TME), 5%–30% of CD4+Foxp3+ Treg cells have been observed to highly express granzyme B—a feature absent in Treg cells from some mouse models—suggesting that granzyme B production enables Tregs to kill NK cells and CD8+ T cells." (PMID 40297580, 2025). "In order to evaluate the expression levels and topographic distribution profiles of CD4, CD8, Foxp3, CD68, CD163, and CD11c, tissue microarrays of the invasive front as well as the tumor core of BCC and cSCC samples were analyzed." (PMID 41068337, 2025). "FOXP3 modulates the expression of immune checkpoint molecules such as PD-L1 and CTLA-4, enhancing the tumor's ability to escape immune surveillance." (PMID 39883234, 2025). "In terms of infiltrating immune cell distribution, CD20+ B cells, CD8+ T cells, CD4+ T cells, and CD4+ FoxP3+ Treg cells were mainly distributed in the stroma, whereas CD68+ macrophages were concentrated in the tumor parenchyma." (PMID 40710213, 2025).